MKS1 (MKS transition zone complex subunit 1)
Description:
Component of the tectonic-like complex, a complex localized at the transition zone of primary cilia and acting as a barrier that prevents diffusion of transmembrane proteins between the cilia and plasma membranes. Involved in centrosome migration to the apical cell surface during early ciliogenesis. Required for ciliary structure and function, including a role in regulating length and appropriate number through modulating centrosome duplication. Required for cell branching morphology.
Synonyms: FLJ20345; POC12; BBS13; JBTS28; MES; MKS
Tractability: PROTAC: ubiquitination databases record sites on it.
Gene: Protein-coding gene on chromosome 17 (58,205,350 to 58,219,605, reverse strand). Ensembl gene ENSG00000011143.
Subcellular location: Cytoplasm, cytoskeleton, cilium basal body; Cytoplasm, cytoskeleton, microtubule organizing center, centrosome
Subcellular location (Human Protein Atlas): Basal body; Nucleoli; Nucleoplasm
Pathways (Reactome):
Organelle biogenesis and maintenance: Anchoring of the basal body to the plasma membrane
Signal Transduction: Hedgehog 'off' state
Gene Ontology:
Molecular function: protein binding
Biological process: cilium assembly; protein localization to ciliary transition zone; branching morphogenesis of an epithelial tube
Cellular component: centrosome; ciliary basal body; cytoplasm; ciliary transition zone; cytosol; MKS complex; centriole; cilium; membrane
Genetic constraint (gnomAD): Loss-of-function variants: 70 observed, 86.19 expected, observed/expected ratio (o/e) 0.81, 90% interval 0.67 to 0.99. The upper end of that interval is the gene's LOEUF score, 0.99, which puts it in group 4 of 6, group 1 being the genes least tolerant of losing a copy. Missense variants: 681 observed, 748.01 expected, observed/expected ratio (o/e) 0.91, 90% interval 0.85 to 0.97. Synonymous variants: 251 observed, 279.79 expected, observed/expected ratio (o/e) 0.9, 90% interval 0.81 to 1.
Gene-disease validity (ClinGen):
ClinGen rates the evidence that MKS1 causes each of these diseases.
ciliopathy (autosomal recessive): Definitive. A genetic disorder of the cellular cilia or the cilia anchoring structures, the basal bodies, or of ciliary function.
Homologues: Orthologues: chimpanzee MKS1 (99% identical), macaque MKS1 (98% identical), mouse Mks1 (89% identical), guinea pig MKS1 (89% identical), rabbit MKS1 (88% identical), rat Mks1 (87% identical), pig MKS1 (85% identical), dog MKS1 (84% identical), tropical clawed frog mks1 (61% identical), zebrafish mks1 (59% identical), Drosophila melanogaster Mks1 (16% identical), Caenorhabditis elegans mks-1 (15% identical). Paralogues in human: B9D2 (11% identical), B9D1 (11% identical).
Diseases named in the same sentence as MKS1 in open-access papers:
MKS1 is named in the same sentence as 27 diseases in open-access papers, as found by Europe PMC text mining. Sharing a sentence is not in itself a finding about the gene and the disease. The quoted sentences say what the papers report.
ciliopathy (20 papers, 2014 to 2025). "Patient IRD-26 presented with variants in two genes, ALMS1 and MKS1, which are typically linked to syndromic ciliopathies, including Alström syndrome, Meckel syndrome, Bardet–Biedl syndrome, and Joubert syndrome." (PMID 41465088, 2025). "Many proteins that are mutated in ciliopathies, including the MKS1 protein, localise to the transition zone (TZ), a compartment of the proximal region of the cilium." (PMID 35170427, 2022). "A clinical exome identified biallelic nonsense variants in MKS1 that prompted post-genotyping investigations for systemic abnormalities of ciliopathy." (PMID 34359301, 2021). "Mutations in TMEM67 are responsible for 16% of all MKS cases, being the most common cause of this ciliopathy, followed by MKS1 mutations, which account for 7% of MKS cases." (PMID 33748110, 2021). "Taken together, these findings suggested that the genotype–phenotype correlation is more complicated in MKS1-mutated ciliopathies." (PMID 33193692, 2020). "Mks1 and Cc2d2a are both part of a large complex of proteins implicated in human ciliopathies localized to the transition zone of cilia." (PMID 27207957, 2016). "The same method was subsequently used to unravel the functional modules associated with nine ciliopathy-associated bait proteins, NPHP1–NPHP6, NPHP8, AHI1 and MKS1, identified in the ciliopathies nephronophthisis (NPH), Joubert syndrome (JBTS) and Meckel–Gruber syndrome (MKS) (see Glossary)." (PMID 41164956, 2025). "Pathogenic variants in the MKS1 gene are responsible for a ciliopathy with a wide spectrum of clinical manifestations ranging from Meckel and Joubert syndrome (JBTS) to Bardet-Biedl syndrome, and involving the central nervous system, liver, kidney, skeleton, and retina." (PMID 34359301, 2021). "TCTN1 is also a known protein component of a ciliopathy-associated protein complex and could interact with Mks1, Tmem216, Tmem217, and several other proteins that are associated with ciliopathies to modulate ciliary assembly and trafficking." (PMID 31297133, 2019). "Three mutations are in known ciliopathy genes, mks-1, mks-2 and mks-5." (PMID 26863025, 2016). "To substantiate an in vivo association between de-regulated canonical Wnt signalling and proteasome activity in the ciliopathy disease state, we crossed the Mks1 knock-out mouse line with the UbG76V-GFP transgenic reporter line." (PMID 35170427, 2022). "Mutations in the MKS1 gene cause about 15% of MKS, a lethal neurodevelopmental condition that is the most severe ciliopathy." (PMID 35170427, 2022). "This work expands the mutation spectrum of MKS1 and elucidates the clinical heterogeneity of MKS1-related ciliopathies." (PMID 33193692, 2020). "TCTN1, for example, forms a biochemical complex at the TZ with CC2D2A, other ciliary transmembrane proteins (TCTN2, TMEM216, and TMEM67), and other known ciliopathy proteins (MKS1, CEP290, and B9D1)." (PMID 29209597, 2017). "The highest intensity points of TMEM67 and TCTN2 occurred at the same axial level as MKS1 and RPGRIP1L, indicating a special axial level accommodating these ciliopathy-associated proteins." (PMID 26365165, 2015). "In patients with a variety of syndromic ciliopathies attributed to variants in NPHP3, IQCB1, CEP290, and MKS1, a common RPGRIP1L variant (p.Arg229Thr) (present in over 8% of South Asians and 3% of other populations) is significantly enriched in patients who also have retinitis pigmentosa." (PMID 37628633, 2023). "However, mutation in MKS1 can cause BBS, and mutation in BBS4 (MIM 600374) can modify the ciliopathy phenotypes of CEP290 (MIM 610142), suggesting that the BBSome and transition zone may share some functions." (PMID 26540106, 2015). "MKS Transition Zone Complex Subunit 1 (MKS1) is necessary for ciliated epithelial cells to form primary cilia, and MKS1 mutant can also form the duplex kidney, which is a part of a ciliopathy phenotype." (PMID 37159529, 2023).
Meckel syndrome (10 papers, 2007 to 2025). "MKS1, the gene encoding the protein associated with Meckel syndrome type 1, has been identified as a pleiotropic modifier gene in Bardet-Biedl syndrome (BBS)." (PMID 36552829, 2022). "Mutations in Mks1 gene associated with Meckel-Gruber syndrome perturb Hedgehog signaling in a mouse model." (PMID 32276433, 2020). "Clinical features in MKS3 closely resemble those in Meckel syndrome type 1 (caused by mutations in MKS1); although in MKS3, polydactyly and encephalocoele are less frequent." (PMID 28487520, 2017). "Here we describe four patients with mild Joubert phenotypes who carry pathogenic mutations in either MKS1 or B9D1, two genes previously implicated only in Meckel syndrome." (PMID 24886560, 2014). "One human B9 domain protein, MKS1, is known to be involved in the human Meckel-Gruber syndrome." (PMID 17875208, 2007).
Bardet-Biedl syndrome (4 papers, 2021 to 2025). A ciliopathy with multisystem involvement. "Our study revealed that individuals carrying heterozygous mutations in the MKS1 gene, specifically the rs199910690 variant associated with Bardet-Biedl syndrome, had an elevated risk of overweight and obesity." (PMID 38617006, 2024).
Meckel syndrome, type 1 (4 papers, 2016 to 2024). Any Meckel syndrome in which the cause of the disease is a mutation in the MKS1 gene. "Sternal ossification defects and formation of pre-axial polydactylous triphalangeal thumbs preferentially in the hind limbs have been described in two different mouse models of Meckel-Gruber syndrome gene Mks1—kerouac and Mksdel64-323 and demonstrated to be caused by disruptions in Hh signaling." (PMID 27224062, 2016).
Obesity (3 papers, 2014 to 2024). Accumulation of substantial excess body fat. "With regard to the risk allele in the BBS group, more specifically in our study, the variant rs199910690 in MKS1 showed evidence of associations with overweight and obesity." (PMID 38617006, 2024). "The variant rs199910690 in MKS1 revealed an increased risk of overweight and obesity." (PMID 38617006, 2024). "In addition, ROHs at 9q21.33-q22.2 and 17q22-q23.2 were found and contained genes (NTRK2, MKS1) that may play a role in obesity and developmental or speech delay." (PMID 25400949, 2014). "MKS1 is a TZ protein found in MKS, JBTS, and Bardet–Biedl syndrome (BBS), which is a ciliopathy characterized by obesity, retinitis pigmentosa, polydactyly, intellectual disability, and renal abnormalities." (PMID 33193692, 2020).
nephronophthisis (2 papers, 2023 to 2024). Progressive tubulointerstitial injury, inherited in an autosomal recessive pattern, caused by mutations in genes involved in ciliary function, which may result in an end stage renal failure. "Seventeen patients carried heterozygous variants in at least one of 13 other genes (including NPHP4, RPGRIP1L, TMEM216, CC2D2A, and MKS1) implicated in nephronophthisis or associated syndromes, suggesting modified genetic activity." (PMID 37628633, 2023). "In patients with syndromic nephronophthisis caused by several genes (including NPHP3, IQCB1, CEP290, and MKS1), an additional heterozygous variant in RPGRIP1L is associated with retinitis pigmentosa." (PMID 37628633, 2023). "Common variants are associated with elevated creatine in association studies;In patients with syndromic nephronophthisis caused by several genes (including NPHP3, IQCB1, CEP290, and MKS1), an additional heterozygous variant in RPGRIP1L is associated with retinitis pigmentosa." (PMID 37628633, 2023).
renal cystic disease (2 papers, 2011 to 2012). "In summary, our findings for MKS1 and MKS3 support the hypothesis that proteinsassociated with renal cystic disease play important roles in modulating theproper expression and/or localization of a subset of OE ciliary proteins, and inthe maturation of OSNs." (PMID 21614130, 2011).
retinal degeneration (2 papers, 2022). Degeneration of the retina. "Only in two individuals, optic atrophy occurred in association with retinal degeneration, respectively, in a patient with MKS1‐ and in a patient with INPP5E‐related JS." (PMID 35238134, 2022). "Alternatively, because mks1 has a strong role in neuromast sensitivity to neomycin and retinal degeneration, its function could be restricted to non-motile cilia." (PMID 36533556, 2022).
chronic kidney disease (1 paper, 2024). Impairment of the renal function secondary to chronic kidney damage persisting for three or more months. "However, regardless of their body mass index (BMI), individuals possessing the CA/AA genotype for BBS2 rs773862084 or the CT/TT genotype for MKS1 rs199910690 did not exhibit an increased risk of developing chronic kidney disease (CKD)." (PMID 38617006, 2024).
developmental delay (1 paper, 2020). "In this study, we report a JBTS patient with two novel MKS1 mutations displaying global developmental delay, MTS, and hypotonia." (PMID 33193692, 2020).
melanoma (1 paper, 2020). A malignant, usually aggressive tumor composed of atypical, neoplastic melanocytes. "Finally, Mks1 encodes the Meckel syndrome-associated protein that mediates ciliary trafficking; the loss of primary cilium was shown to drive melanoma metastasis via WNT/β-catenin signaling." (PMID 32831131, 2020).
infection (7 papers, 2010 to 2022). The state of being infected such as from the introduction of a foreign agent such as serum, vaccine, antigenic substance or organism. "For instance, activation of MPK4 by bacterial elicitors caused MKS1 phosphorylation of WRKY33 in MPK4 complexes and then functioned in pathogen infection." (PMID 35887014, 2022). "MKS1 phosphorylation by MPK4 occurs following pathogen infection, leading to WRKY33-induced expression of PAD3, which is required for biosynthesis of the antimicrobial phytoalexin, camalexin." (PMID 30261844, 2018). "It was shown that MPK4 and MKS1 associate in a complex with WRKY33, and that activation of MPK4 and phosphorylation of MKS1 upon infection leads to release of MKS1 and WRKY33 from MPK4." (PMID 21203436, 2010). "The increased expression of BAK1, MKK1/2, MKS1, MPK, MPK3/6, ACS6, WRKY TF, PR1, and FRK1 in NOWP and/or NOWS proposes that N. indicum responds to witches’ broom infection by both the early and late defense responses." (PMID 35701735, 2022). "WRKY33 forms a complex with MAP KINASE SUBSTRATE1 (MKS1), a substrate of MAPK4, and upon pathogen infection or elicitor treatment, activated MAPK4 phosphorylates MKS1 and releases WRKY33 from the complex." (PMID 34618142, 2021). "MKS1, a MPK4-substrate, is required for basal resistance against pathogen infection." (PMID 35887014, 2022).
MKS1 also shares sentences with these, for which no sentence is quoted: Joubert syndrome (8 papers); retinitis pigmentosa (2); Alström syndrome (1); Bardet-Biedl syndrome type 13 (1); congenital nephrotic syndrome (1); diabetes mellitus (1); Hepatic fibrosis (1); hyperlipidemia (1); Hypertension (1); Kidney Cyst (1); polydactyly (1); Pulmonary hypoplasia (1); renal carcinoma (1); retinal diseases (1); speech delay (1).